DCN (decorin)
Diseases named in the same sentence as DCN in open-access papers (continued):
Sharing a sentence is not in itself a finding about the gene and the disease.
glioma (continued). "It was not a surprise when we found that DCN‐mediated suppression of glioma cell migration was correlated with the inhibition of TGF‐β activity." (PMID 27398310, 2016). "Decorin (DCN) is a major member of the small leucine‐rich proteoglycan (SLRP) family that is critically involved in tumorigenesis and the development of metastasis of cancers, including glioma." (PMID 27398310, 2016). "This differential expression was also observed in cultured cells that a higher decorin expression found in normal astrocyte cell line NHAs while it was at low levels in established glioma cells (U87MG, T98G, U251, A172 and U118) and the glioma cells isolated from three GBM patients." (PMID 34386415, 2021). "Taken together, the increased DCN levels in glioma tissues may turn out not to be a factor participating in glioma progression as initially suspected, rather it implies that decorin acts as a suppressor for both cancer growth and metastasis." (PMID 27398310, 2016). "Further studies are needed to elaborate the interrelations among DCN, autophagy, and TMZ, where autophagy inhibitors like Chloroquine (CQ) and its derivative HCQ could be considered, as these compounds are now being tested for trials in glioma treatments." (PMID 27398310, 2016). "Decorin was well known to exert suppressive effects on the growth of tumors, and its effect on the migration was investigated in several cancer types 29, 30, 31, 32, but not yet for gliomas prior to our current study." (PMID 27398310, 2016). "However, the relation between decorin, EMT and c-Met/Akt/mTOR axis remains unclear in glioma cells." (PMID 34386415, 2021).
prostate carcinoma (24 papers, 2012 to 2026). A carcinoma that arises from epithelial cells of the prostate gland. "Specifically, decorin and lumican have shown inhibitory effects on prostate cancer progression, whereas the basement membrane proteoglycan perlecan has been identified as a tumor promoter." (PMID 39771106, 2024). "The expression of SPARC and DCN is significantly higher in prostate cancer cell lines that actively invade the astrocyte monolayer." (PMID 34503278, 2021). "In prostate cancer cell models, decorin prevents androgen receptor nuclear translocation and inhibits the production of PSA." (PMID 32056047, 2020). "In an animal model, systemic administration of decorin significantly reduced prostate cancer bone metastasis." (PMID 32056047, 2020). "The observed MEIS-mediated increase in DCN mRNA and protein expression was also observed in a third prostate cancer cell line, VCAP." (PMID 32553107, 2020). "VCAN has been shown to be up-regulated in prostate cancer along with the PGs syndecan-1, perlecan, decorin, biglycan, neural/glial antigen, serglycin and lumican." (PMID 32354091, 2020). "Several proteoglycans have been found to be important in prostate cancer, including versican, decorin, biglycan, lumican, and syndecan-1, and data from a range of studies implicate proteoglycan alterations to prostate cancer cell survival and metastasis." (PMID 30893936, 2019). "In prostate cancer, decorin, lumican, and versican were strongly overexpressed, although this study relied on mRNA expression data of the core proteins; thus, conclusions about the actual PG content are difficult." (PMID 32118030, 2019). "For example, an expression of collagens I, II, III, IV, fibromodulin, and proteoglycans (decorin, biglycan, lumican) in stromal cells, when grown in the presence of two metastatic prostate cancer cell lines PC3 and DU145, is significantly down-regulated." (PMID 24782989, 2014). "Systemic delivery of decorin to prostate-specific Pten(P−/−) mice, a genetically defined, immune-competent mouse model of prostate cancer, inhibits tumour progression by targeting cell proliferation and survival pathways." (PMID 23691363, 2013). "The most studied proteoglycans in prostate cancer include extracellular proteoglycans versican, decorin and perlecan, and cell surface proteoglycans syndecan-1 and betaglycan." (PMID 23691363, 2013). "Decorin and Tsukushi were the only candidates with stromal-only expression and were subsequently investigated in prostate cancer (PCa) tissues." (PMID 22880013, 2012). "We identified Decorin as a stromally restricted molecule whose expression was down-regulated in prostate cancer." (PMID 22880013, 2012). "Decorin showed mesenchymal and stromal-specific expression at all ages and was further examined in prostate cancer, where stromal expression was significantly reduced compared with non-malignant prostate." (PMID 22880013, 2012). "We decided to focus on molecules showing mesenchyme-only expression and thus Decorin and Tsukushi were taken forward for evaluation of expression in prostate cancer and patient-matched controls." (PMID 22880013, 2012). "We identified Decorin as a stromally expressed molecule and examined if it showed altered expression in prostate cancer (PCa) stroma." (PMID 22880013, 2012). "Further studies into Decorin’s potentially tumour suppressive effects in prostate cancer are warranted." (PMID 22880013, 2012). "Four candidates (Decorin, SPARC, Spry-1, Tsukushi) were immunolocalised in human foetal prostate (weeks 14, 16, 19) and expression of Decorin was evaluated on a human prostate cancer tissue microarray." (PMID 22880013, 2012). "One of these molecules, the putative tumour suppressor Decorin, also showed downregulation in prostate cancer stroma." (PMID 22880013, 2012).
prostate carcinoma (continued). "In prostate cancer, PGs have been shown to be involved in many steps of its progression; the most prominent examples include the seemingly tumor-promoting roles of versican, perlecan, and biglycan, and the tumor-suppressive roles of decorin and betaglycan." (PMID 41470114, 2025). "DCN, a small leucine-rich proteoglycan, is a tumor suppressor in prostate cancer." (PMID 34321013, 2021). "Other PGs may also play a role, particular those that are up-regulated in prostate cancer, such as syndecan-1, perlecan, decorin, biglycan, neural/glial antigen 2, serglycin and lumican." (PMID 32354091, 2020). "In addition, decorin transfer inhibited Met and Wnt/β-catenin signaling pathways and thus prevented the formation of bone metastasis of prostate cancer cells." (PMID 32477937, 2020). "However, our finding of Decorin down-regulation in PCa is supported by its activity as a tumour suppressor in prostate cancer and further investigation of Decorin in prostate cancer is likely to be of value." (PMID 22880013, 2012). "It was also demonstrated that exogenous decorin inhibited the growth of androgen-independent (PC3 and DU-145) and androgen-dependent (LNCaP) prostate cancer cells." (PMID 41210271, 2025). "Unlike the other class I SLRPs (decorin and biglycan), asporin contains a unique and conserved stretch of aspartate (D) residues in its N terminus, and germline polymorphisms in the D-repeat-length are associated with osteoarthritis and prostate cancer progression." (PMID 31608236, 2019). "We further determined whether DCN-tCRK binds to the cells that express NRP-1, i.e., human PC3 prostate carcinoma cells." (PMID 32497513, 2020). "It was shown that decorin concentration is increased in the prostatic tissue of men with early-stage prostate cancer or reduced in prostate cancer stroma compared to nonmalignant prostate stroma." (PMID 23691363, 2013). "Additionally, Decorin showed reduced expression in prostate cancer stroma compared to non-malignant prostate stroma." (PMID 22880013, 2012). "Here, we report a phenotypic and mechanistic determination that MEIS proteins promote indolent and non-metastatic prostate cancer via the HOXB13-dependent regulation of extracellular proteoglycans, in particular the multi-RTK inhibitor Decorin." (PMID 32553107, 2020).
melanoma (19 papers, 2008 to 2025). A malignant, usually aggressive tumor composed of atypical, neoplastic melanocytes. "The study inferred that sulforaphane significantly reduced the levels of proinflammatory cytokines in plasma and increased the tumor suppressor decorin in tissues, thus preventing the risk of melanoma." (PMID 37397365, 2023). "In addition, the altered expression of lumican and decorin has been associated with various human cancers including breast, pancreatic, lung, ovarian, melanoma, colorectal, osteosarcoma and ductal adenocarcinoma." (PMID 20540791, 2010). "In contrast, Decorin is reported to function in a tumour suppressive manner and low levels in both melanoma tissue and circulating blood plasma have been correlated with disease progression and decreased survival rates in melanoma patients." (PMID 40654904, 2025). "In line with this, we have previously investigated the interaction between several recombinant VAR2CSA proteins and immobilized bovine decorin, as well as the interaction of rVAR2 with a melanoma cell." (PMID 27441183, 2016). "In another model system, Decorin led to an acidification of the microenvironment and cancer cells, resulting in the inhibition of migrating melanoma cells in a co-culture system with fibroblasts." (PMID 22880013, 2012). "LUM, whose expression is down regulated in most metastatic melanomas, is another member of the family of small proteoglycans that includes decorin for which an anti-invasive role was reported." (PMID 18211678, 2008). "Many of these downregulated proteomic cargoes in melanoma sEVs, including collagens (COL1A1, COL3A1, COL6A1–A3, and COL14A1), matrix-associated proteoglycans (DCN, LUM, FMOD, OGN, and PRELP), and structural regulators (TNXB and PCOLCE), are key components of ECM organization and tensile strength." (PMID 41271007, 2025). "We showed previously that DS decorin reduces the pericellular pH of melanoma cells." (PMID 23226541, 2012). "Interestingly, the DS proteoglycan decorin inhibits melanoma cell migration by reversibly acidifying the cell surface pH to an intermediate value of 7.1, where migration reaches its maximum." (PMID 23226541, 2012). "A smaller tissue from patient ID 9561, collected in 2008, had four clusters, including melanoma (PMEL, TYRP1), immune cells (TMSB4X, IL32), keratinocytes (KRT10, KRT1, DSG1), and fibroblast areas (COL1A2, COL1A1, DCN)." (PMID 39846232, 2025). "The results showed that the expression of DSC3, DLL3, BMP6, SEMA4D, and GHRH are increased (p < 0.05) in melanoma, while the expression of LRRC4B, SFRP1, DCN, and CCL-8 decreased in melanoma (p < 0.05)." (PMID 36777724, 2023). "Previous studies have shown the ability of lumican (and its derived peptides), in contrast to decorin (DCN), to inhibit MMP-14 activity in melanoma cells, where lumican directly interacted with MMP-14." (PMID 34885059, 2021). "We defined clusters corresponding to melanoma (PMEL, MLANA), immune infiltrates (TRBC2, TRAC, TMSB4X), melanophages (CD74, LYZ), keratinocytes (KRT14, TRIM29), blood vessels (CAVIN1, PECAM), and fibroblast‐enriched areas in the dermis (DCN, COL1A2, FBLN1)." (PMID 39846232, 2025). "We observed that the genes DCN (decorin), LUM (lumican) and BGN (Bgn), which are members of the small leucine-rich proteoglycan (SLRP) family, were within the highest expressed ECM genes in both melanoma cells and fibroblasts." (PMID 28476030, 2017).
Obesity (18 papers, 2013 to 2026). Accumulation of substantial excess body fat. "We investigated the effects of decorin deficiency on obesity, glucose tolerance, and exercise adaptation in C57BL/6J mice." (PMID 40616270, 2025). "SPARC and DCN were associated with insulin resistance and obesity." (PMID 35627183, 2022). "We here studied the impact of loss of decorin on obesity-related phenotypes, hypothesizing that decorin plays an important role in the regulation of body weight, glucose tolerance and adipose tissue function." (PMID 30874564, 2019). "In particular, collagen VI is highly expressed in adipose tissue and plays a key role in the fibrosis associated with obesity, thus its degradation, promoted by decorin, may counteract the development of adipose tissue fibrosis and so it could be leveraged for therapeutic purposes." (PMID 33409282, 2020). "Conversely, expression of the accessory protein decorin (DCN) is elevated with obesity and has a positive prognostic value." (PMID 40847127, 2025). "Obesity is associated with increasing some members of the TGF-β family such as MST and activin A and DCN and diminished FST concentration." (PMID 39275173, 2024). "Obesity is often accompanied by low-grade inflammation, and decorin has been shown to act as a proinflammatory molecule." (PMID 38136166, 2023). "Decorin expression in adipose tissue is increased in obese patients and has been proposed to mediate adipose tissue activity in obesity." (PMID 35757424, 2022). "Here, we show that MT1-MMP (also known as MMP14), a collagenase highly expressed in AT and further induced in obesity, is co-expressed with DCN in ASC and cleaves DCN to generate ΔDCN." (PMID 33317052, 2020). "This study reveals that the GAG of DCN functions to regulate collagen assembly in adipose tissue and skeletal muscle and uncovers a new mechanism of matrix dysfunction in obesity and aging." (PMID 33317052, 2020). "Previous studies of rodents and humans with obesity and glucose intolerance have suggested increased expression of decorin mRNA in whole adipose tissue and secreted decorin protein in plasma." (PMID 30874564, 2019). "Studies have shown that rodents and humans with obesity and glucose intolerance have increased expression of decorin in adipose tissue." (PMID 30874564, 2019). "Among others, DPP4, PEDF as well as MCP-1, decorin and PAI-1 are described to be associated with conditions of obesity, insulin resistance and diabetes." (PMID 23637948, 2013). "Little is known regarding the effect of decorin on obesity or insulin resistance." (PMID 40616270, 2025). "Decorin is a small leucine-rich proteoglycan that increases in concentration in response to fat accumulation and its related inflammatory and metabolic changes during obesity." (PMID 39275173, 2024). "The obesity pathogenesis involves dysregulated secretion of collagens as well as of DCN." (PMID 33317052, 2020). "Furthermore, recently, it has been reported that the small leucine-rich proteoglycans lumican and decorin have an important role in EMT occurring during fibrosis in obesity, but with contrasting final effects." (PMID 33409282, 2020). "However, studies continue to identify new adipokines and myokines, such as nesfatin-1, neuregulin 4, myonectin, irisin, BDNF, decorin, visfatin, and chemerin, which may participate in the development of obesity-related diseases." (PMID 38136166, 2023). "It has been shown that decorin may have significant implications for obesity and AT metabolism." (PMID 38136166, 2023). "Based on these results, it is difficult to attribute a specific role to decorin in obesity, although it has been observed that its concentration may be increased in obese subjects, as compared with non-obese people and with individuals with impaired glucose tolerance." (PMID 38136166, 2023).
Obesity (continued). "Recent studies have shown that decorin not only exerts its actions within the tumor stroma, but also acts as a multifunctional signaling molecule in numerous pathological conditions such as hepatic fibrosis, immunomodulation, obesity and tumor initiation and progression." (PMID 34386415, 2021). "Compared to the normal pregnancy group, the levels of DCN and ADAMTS12 showed an increasing trend in the gestational obesity group and the GDM group." (PMID 41876836, 2026). "Mechanistically, obesity increases platelet‐derived growth factor (PDGF) receptor expression in uNK cells, leading to an exaggerated response to PDGF and promoting excessive decorin (DCN) expression." (PMID 40325291, 2025). "This study investigated the effects of three different interval resistance training (IRT) protocols and their effects on anthropometric indices, cardiometabolic markers, and levels of decorin, follistatin, myostatin, activin A, TGF-β1 in men with obesity." (PMID 35757424, 2022). "We determined the effects of IRT on the levels of select myokines (decorin, follistatin, myostatin, activin A, TGF-β) and cardiometabolic and anthropometric measures in males with obesity." (PMID 35757424, 2022). "Notably, DCN and ADAMTS12 were markedly higher in the GDM with obesity group compared to either the gestational obesity or GDM-alone groups." (PMID 41876836, 2026). "In conclusion, the absence of decorin did not influence the development of obesity or glucose intolerance and had no major effects on skeletal muscle fiber size or expression of genes related to metabolism, myogenesis, or ECM formation." (PMID 40616270, 2025). "Although it has been well documented that AST can eliminate the detrimental consequences triggered by obesity, there is scant evidence about its effects on changes in adipocytokines and myokines including TGF-β1, activin A, MST, FST, and DCN, which have cardinal roles during obesity." (PMID 39275173, 2024). "As in the case of decorin above, there are, unfortunately, no studies relating obesity phenotypes to BDNF action." (PMID 38136166, 2023). "In a high-fat diet model of obesity in mice, both decorin and TGFβ1 were significantly enhanced in the ECM surrounding mammary epithelial cells, and complexes of decorin and latent TGFβ1 were identified in ECM isolated from breast tissue from women with obesity." (PMID 35435599, 2022). "DCN is highly expressed in white adipose tissue (WAT), in particular in obesity." (PMID 33317052, 2020). "In summary, our study indicates that DCN lacking GAG is generated by cleavage with MMP14 and suggests that MMP14 induction in obesity is responsible for the accumulation of DCN lacking GAG." (PMID 33317052, 2020).